CDC23 (cell division cycle 23)
Description:
Component of the anaphase promoting complex/cyclosome (APC/C), a cell cycle-regulated E3 ubiquitin ligase that controls progression through the cell cycle. APC/C acts by mediating ubiquitination and subsequent degradation of target proteins: it mainly mediates the formation of 'Lys-11'-linked polyubiquitin chains and, to a lower extent, the formation of 'Lys-48'- and 'Lys-63'-linked polyubiquitin chains. APC/C catalyzes assembly of branched 'Lys-11'-/'Lys-48'-linked branched ubiquitin chains on target proteins. APC/C is activated by CDC20 in the metaphase/anaphase transition of cell cycle, targeting the degradation of cyclin B and securin. APC/C is regulated by the mitotic checkpoint complex (MCC), which inhibits APC/C and delays chromosome segregation.
Synonyms: APC8; ANAPC8; CUT23
Tractability: PROTAC: UniProt records ubiquitination sites on it; ubiquitination databases record sites on it; its protein half-life has been measured.
Gene: Protein-coding gene on chromosome 5 (138,187,644 to 138,213,343, reverse strand). Ensembl gene ENSG00000094880.
Pathways (Reactome):
Cell Cycle: APC-Cdc20 mediated degradation of Nek2A; APC/C:Cdc20 mediated degradation of Cyclin B; APC/C:Cdc20 mediated degradation of Securin; APC/C:Cdc20 mediated degradation of mitotic proteins; APC/C:Cdh1 mediated degradation of Cdc20 and other APC/C:Cdh1 targeted proteins in late mitosis/early G1; Autodegradation of Cdh1 by Cdh1:APC/C; Cdc20:Phospho-APC/C mediated degradation of Cyclin A; Conversion from APC/C:Cdc20 to APC/C:Cdh1 in late anaphase; Inactivation of APC/C via direct inhibition of the APC/C complex; Phosphorylation of the APC/C; Regulation of APC/C activators between G1/S and early anaphase; Separation of Sister Chromatids
DNA Replication: Assembly of the pre-replicative complex; CDK-mediated phosphorylation and removal of Cdc6
Cellular responses to stimuli: Senescence-Associated Secretory Phenotype (SASP)
Disease: Aberrant regulation of mitotic exit in cancer due to RB1 defects
Gene expression (Transcription): Transcriptional Regulation by VENTX
Immune System: Antigen processing: Ubiquitination & Proteasome degradation
Gene Ontology:
Molecular function: protein binding; enzyme-substrate adaptor activity; ubiquitin-protein transferase activity
Biological process: anaphase-promoting complex-dependent catabolic process; mitotic cell cycle; mitotic metaphase chromosome alignment; protein branched polyubiquitination; protein K11-linked ubiquitination; protein K48-linked ubiquitination; regulation of mitotic metaphase/anaphase transition; cell division; metaphase/anaphase transition of mitotic cell cycle; positive regulation of mitotic metaphase/anaphase transition; protein ubiquitination; regulation of exit from mitosis; regulation of meiotic cell cycle; regulation of mitotic cell cycle; ubiquitin-dependent protein catabolic process
Cellular component: anaphase-promoting complex; cytosol; nucleoplasm
Genetic constraint (gnomAD): Loss-of-function variants: 25 observed, 77.19 expected, observed/expected ratio (o/e) 0.32, 90% interval 0.23 to 0.45. The upper end of that interval is the gene's LOEUF score, 0.45, which puts it in group 2 of 6, group 1 being the genes least tolerant of losing a copy. Missense variants: 495 observed, 720.06 expected, observed/expected ratio (o/e) 0.69, 90% interval 0.64 to 0.74. Synonymous variants: 250 observed, 273.47 expected, observed/expected ratio (o/e) 0.91, 90% interval 0.82 to 1.01.
Homologues: Orthologues: chimpanzee CDC23 (99% identical), macaque CDC23 (99% identical), rabbit CDC23 (99% identical), guinea pig CDC23 (98% identical), pig CDC23 (98% identical), rat Cdc23 (96% identical), mouse Cdc23 (95% identical), tropical clawed frog cdc23 (87% identical), zebrafish cdc23 (78% identical), Drosophila melanogaster Cdc23 (47% identical), Caenorhabditis elegans mat-3 (34% identical), Drosophila melanogaster CG31687 (26% identical). Paralogues in human: CDC27 (21% identical), CDC16 (17% identical), ANAPC7 (14% identical).
Diseases named in the same sentence as CDC23 in open-access papers:
CDC23 is named in the same sentence as 15 diseases in open-access papers, as found by Europe PMC text mining. Sharing a sentence is not in itself a finding about the gene and the disease. The quoted sentences say what the papers report.
breast carcinoma (3 papers, 2019 to 2024). "CDC23, among others, is a direct target of miR‐34b/c,37, 44 and our results confirmed that miR‐34b/c‐5p reduced its expression level in breast cancer." (PMID 30334298, 2019). "CDC23, regulated by mir-34c, may be responsible for mir-34c-induced cell cycle arrest, where miR-34c can induce G2/M cell cycle arrest in breast cancer cells." (PMID 38418940, 2024).
colon cancer (3 papers, 2005 to 2015). "Gene alterations in several components of the APC/C complex, including APC6/CDC16 and APC8/CDC23, have been found in human colon cancers." (PMID 27030811, 2015).
colorectal cancer (2 papers, 2006 to 2014). A primary or metastatic malignant neoplasm that affects the colon or rectum. "CDC23 mRNA has been shown to be pulled-down as well as downregulated by miR-34a in colorectal cancer cells and downregulated by miR-34c in prostate cancer cells." (PMID 25064703, 2014).
glioblastoma (2 papers, 2021 to 2024). The most malignant astrocytic tumor (WHO grade IV). "In support of the DYRK1A-CDC23 axis controlling glioblastoma cell cycle, CDC23 knockdown increased the percentage of Ki67-positive cells, the number of mitotic figures and overall cell numbers." (PMID 33863878, 2021).
papillary thyroid cancer (2 papers, 2021 to 2022). "Previous studies have demonstrated that LINC00514 accelerates cell proliferation and invasion in vitro and aggravates tumor growth by targeting the miR-204-3p/CDC23 axis in papillary thyroid cancer." (PMID 33757509, 2021). "CDC23 regulates the tumour cell phenotype and is upregulated in papillary thyroid cancer." (PMID 35814454, 2022).
prostate carcinoma (2 papers, 2014 to 2019). A carcinoma that arises from epithelial cells of the prostate gland. "One member of the anaphase-promoting complex (APC), CDC23, has been reported to be a target of miR-34a and show a decreased mRNA expression in response to miR-34c in prostate cancer cells." (PMID 25064703, 2014). "For example, HOXC6 and DLX1 genes, which are biomarkers and key players of prostate cancer development as well as genes involved cell cycle (CDK4, CDC23, MYC) and androgen signaling (AR, GRHL2) are found." (PMID 31515496, 2019).
female infertility (1 paper, 2024). Diminished or absent ability of a female to achieve conception. "Since CDC23 is a key protein for oocyte cell cycle progression and the biallelic mutations in CDC23 cause human OMD and female infertility, we determined whether CDC23 is a downstream effector of PATL2 in cell cycle regulation." (PMID 39741299, 2024).
liver cancer (1 paper, 2025). An epithelial or non-epithelial malignant neoplasm that arises from the liver. "CDC23, one of the APC subunits involving cell mitosis, was reportedly associated with cell cycle progression in liver cancer cell lines, since shRNA‐mediated knockdown repressed cell proliferation." (PMID 40022573, 2025).
thyroid cancer (1 paper, 2022). "CDC23 is a critical regulator of cell cycle and cell growth, and may involve with thyroid cancer initiation and progression." (PMID 36006904, 2022).
cancer (4 papers, 2018 to 2024). A tumor composed of atypical neoplastic, often pleomorphic cells that invade other tissues. "In addition, mutations have been observed in several APC subunit genes (APC3, APC6/CDC16, and APC8/CDC23) in cancer cells." (PMID 29954095, 2018). "Our results revealed that CDC23 exhibits widespread expression in various tissues and organs, and its high degree of expression in the PK15 cell line provides additional evidence for its role in cancer." (PMID 38612477, 2024).
tumour (4 papers, 2002 to 2022). "Surprisingly, that study also showed that let-7 represses several tumour suppressor genes (BRCA1, BRCA2, FANCD2, and PLAGL1, among others) and checkpoint regulators (CHEK1, BUB1, BUB1B, MAD2L1, and CDC23, among others)." (PMID 20179807, 2010).
infection (1 paper, 2013). The state of being infected such as from the introduction of a foreign agent such as serum, vaccine, antigenic substance or organism. "We validated by qRT-PCR the downregulation of the cell division cycle pathway genes (CDC27 and CDC23) in HEK293T and human dermal fibroblasts upon infection with CHIKV." (PMID 24278205, 2013).
CDC23 also shares sentences with these, for which no sentence is quoted: bladder cancer (1 paper); thyroid tumor (1); virus infection (1).